APOC1 (apolipoprotein C1)
Diseases named in the same sentence as APOC1 in open-access papers (continued):
Sharing a sentence is not in itself a finding about the gene and the disease.
cancer (continued). "In MiaPaCa-2 cancer cells, cerivastatin, pitavastatin, and simvastatin increased the expression of the APOC1 gene, the product of which, together with APOE and other apolipoproteins, is an essential component of high-density lipoprotein (HDL), very low-density lipoprotein (VLDL), and chylomicrons." (PMID 40722786, 2025). "However, the precise mechanisms by which APOC1 influences angiogenesis and cancer progression require further investigation." (PMID 39873475, 2025). "We explored them utilizing the pathway activity module of the GSCALite platform to determine whether these six genes (TYROBP, FCER1G, CD48, LST1, APOE, and APOC1) act through specific cancer pathways." (PMID 38515073, 2024). "Previous studies have suggested that APOC1 may serve as a potential biomarker for various cancers, and our analysis indicates its potential as a biomarker for OV as well." (PMID 38515073, 2024). "Recently, studies on APOC1 have increasingly emphasized its involvement in cancer." (PMID 38515073, 2024). "Additionally, we found that TUBA1B+ TAMs, C1QC+ TAMs and IL1B+ TAMs were predominant in early-stage tumors, whereas VCAN+ TAMs, SLC40A1+ TAMs and APOC1+ TAMs had higher proportions in patients with advanced cancer." (PMID 39232806, 2024). "An earlier study found that the mitogenic impact of high-density lipoprotein cholesterol (HDL) on bovine vascular endothelial cells in vitro was caused by APOC1 purified from HDL, and APOC1 has recently been identified as a molecule involved in the advancement of cancer." (PMID 36908705, 2023). "Apolipoprotein C1 (APOC1) was found to be involved in cancer pathogenesis." (PMID 38283351, 2023). "This suggests that APOC1 may be contributing to cancer pathology across diverse cancers in multiple cell types." (PMID 36873459, 2022). "Recently, the relationship between APOC1 and malignant tumors has been highlighted." (PMID 32974161, 2020). "Additionally, some studies revealed that APOC1 acts as an oncogene in the progression of some malignant tumors, including breast, pancreatic, colorectal, and lung cancer." (PMID 32974161, 2020). "It remains unsolved whether higher ApoC1 levels are protective or detrimental in cancer." (PMID 36101402, 2022). "Following calculating high abundance genes in M2 macrophages and cancer cells, we found that PDE4C and APOC1 was both highly enriched in M2 macrophages and cancer cells." (PMID 38774995, 2024). "A greater understanding of the direct interactions between APOC1, APOE, RAB42, and TREM2 in cancer is, however, required due to the paucity of studies in this area." (PMID 36908705, 2023). "In particular, the lipid import gene APOC1 is expressed in cancer progenitor cells, but not in the other cell populations, including normal progenitor cells, from the same patient samples." (PMID 38649187, 2024). "These specific metabolic flux–related genes, such as DNM2 (endocytosis), APOC1 (lipid transport), MRI1 (L-methionine salvage), MTAP (NAD salvage), and SLC29A1 (nucleoside import), indicate that the cancer progenitor cells represent hubs of metabolic trafficking activities." (PMID 38649187, 2024). "Therefore, after cancer tissue is removed from the body after surgery, CA1 and NCHL1 decrease, and APOC1 increases." (PMID 36564525, 2023). "In order to further explore the potential mechanism of the five key genes (APOC1, APOC1P1, ISYNA1, C7orf61 and APOE) and whether these genes functioned through common cancer pathways, we analyzed them using the GSCALite platform by pathway activity module." (PMID 35371313, 2022). "In addition, liver X receptor β (LXRβ) is overexpressed in PTC and induce the expression of its target genes including APOC1, APOC2 and APOE, which may activate lipid metabolism and protein synthesis, thus facilitating cancer cell proliferation." (PMID 36506554, 2022).
cardiovascular disease (13 papers, 2010 to 2026). "Subspecies containing proteins related to inflammation, immune response, thrombosis, and lipid metabolism seem to correlate with an increased risk of cardiovascular disease, while those containing apolipoprotein C1 or E are linked with a reduced risk." (PMID 39022525, 2024). "Because apoB and the apoB/apoA-I ratio have been reported to be better predictors of cardiovascular diseases than traditional lipid measurements, our results provide further evidence that the A → G variant of rs4420638 in the apoC1 gene is associated with cardiovascular disease risk." (PMID 29636060, 2018). "The first example is the APOE gene, a gene which expression has been associated with Alzheimer and cardiovascular diseases and with genetic variants at the TOMM40/APOE/APOC1 locus near the gene also associated with longevity." (PMID 29228364, 2018). "The role of apoC1 in cardiovascular disease remains debatable." (PMID 31779116, 2019). "Interestingly, an integrative system biology analysis, used to evaluate transcriptomic data from 47 microarrays of carotid endarterectomies from the clinical biobank database BiKE, identified an apoC1-centered, “phospholipid efflux” network as an important node in cardiovascular disease." (PMID 31779116, 2019). "Cardiovascular disease highlights CDKN2B-AS1, LPA, and SH2B3; respiratory system disease features CHRNA3; psychiatric disorders highlight APOE, APOC1." (PMID 41166152, 2026). "Higher levels of plasma apoC1 were found in patients who died from cardiovascular diseases when compared to those who did not." (PMID 36471375, 2022).
infection (11 papers, 2009 to 2024). The state of being infected such as from the introduction of a foreign agent such as serum, vaccine, antigenic substance or organism. "Additionally, we identified 10 genomic regions associated with breakthrough infection (SLC6A20, ST6GAL1, MUC16, FUT6, MXI1, MUC4, HMGN2P18-KRTCAP2, NFKBIZ and APOC1), and one with breakthrough severity (APOE)." (PMID 39384777, 2024). "One-fifth of upregulated DEPs in the AD retinas were related to immune responses, including HLA-DRB1, APOC1, S100A1, HLA-E, IBA1, and S100β, and involved lymphocyte and myelomonocyte activation in the presence of neuroinflammation and infection." (PMID 36773106, 2023). "The differential gene expression observed at day 15 post-infection demonstrated a consistent pattern of gene up regulation of PHGDH and PSAT1 and down regulation of APOC1, FADS2, FXYD2, KIAA0125, and MMP12 over a period of time in HIV-1 infected PBMC." (PMID 26821323, 2016). "As seen in infection with HCVcc (JFH1), expression of ApoA1, ApoA2, ApoC1, ApoC2, ApoC3 and ApoE enhanced the formation of infectious particles of TH/JFH1 and S310/JFH1 chimeric viruses." (PMID 25502789, 2014). "The mRNA levels of PPAR target genes associated with adipocyte differentiation, including ADRP, FABP4, CD36, APOE, APOC1, ASCL1, were strongly induced in THP-1 cells at 6 or/and 48 h after infection by M. leprae but not stimulation by dead M. leprae, as showed by real-time PCR." (PMID 33075048, 2020). "An interesting report showed that in systemic post-surgical inflammation, whether accompanied by infection or not, HDL was decreased and depleted in both apoA1 and apoC1, but enriched in apoE." (PMID 31779116, 2019).
neurodegenerative disease (5 papers, 2012 to 2025). A disorder of the central nervous system characterized by gradual and progressive loss of neural tissue and neurologic function. "Of these APOE, APOC1 and ASAH1 are involved in lipid metabolism and neurodegenerative diseases." (PMID 35388616, 2022).
infectious disease (1 paper, 2016). A disorder directly resulting from the presence and activity of a microbial, viral, or parasitic agent in humans. "Because APOC1 activates cholesterol metabolism, its up-regulation leads to an increase in cholesterol biosynthesis, consistent with the concomitant presence of MP infectious disease." (PMID 28018301, 2016).
APOC1 also shares sentences with these, for which no sentence is quoted: liver fibrosis (4 papers); type III hyperlipoproteinemia (4); bacterial infection (3); hemorrhagic stroke (3); papillary thyroid carcinoma (3); polycystic ovary syndrome (3); rheumatoid arthritis (3); angina pectoris (2); asthma (2); Cirrhosis (2); diffuse large B-cell lymphoma (2); kidney disorder (2); Lung Squamous Cell Carcinoma (2); metabolic disease (2); myocardial infarction (2); Stroke (2); abdominal aortic aneurysm (1); acne (1); acute monocytic leukemia (1); acute myeloid leukemia (1); acute-on-chronic liver failure (1); age-related macular degeneration (1); anaplastic astrocytoma (1); autoimmune disease (1); benign breast disease (1); bipolar disorder (1); Breast invasive carcinoma (1); celiac disease (1); cerebral aneurysm (1); cervical squamous cell carcinoma (1).
A further 57 diseases each share a sentence with APOC1 in 1 paper.